IGF1 (insulin like growth factor 1)
Diseases named in the same sentence as IGF1 in open-access papers (continued):
Sharing a sentence is not in itself a finding about the gene and the disease.
hepatocellular carcinoma (continued). "Furthermore, we investigated if PI3K/Akt played a role in the process of glycolysis of hepatoma cells using the PI3K/Akt activator insulin like growth factor 1 (IGF-1) and the AKT inhibitor Akti IV." (PMID 28810896, 2017). "VEGF is closely associated with the development and metastasis of HCC, and inhibition of IGF-1 or HIF-1α may be an promising target for hepatocellular carcinoma." (PMID 25663870, 2015). "Based on earlier findings on the role of IGF1 in low-grade ovarian carcinomas, as well as in in vitro studies in hepatocellular carcinoma, a phase II clinical trial is currently underway using the IGF-1R/IR dual receptor tyrosine kinase inhibitor OSI-906 (clinicaltrials.gov)." (PMID 24237932, 2013). "Similarly, in hepatocytes, the addition of C/EBPβ-LAP in the human hepatoma cell line Hep3B increases IGF-1 expression." (PMID 21854628, 2011). "In vitro data on human hepatoma-culturedcells indicated that insulin-like growth factor 1 (IGF-1) may be a negativeregulator of SHBG synthesis.Upon aging, IGF-1 decreases, reducing the inhibitory effect on SHBG production inhepatocytes, which increases SHBG levels." (PMID 40857627, 2025). "In the case of hepatocellular carcinoma (HCC) HEATR1 is up‐regulated through the IGF1‐mTORC1‐SP1 axis." (PMID 39465903, 2024). "Furthermore, the expression of exosomal miR-122 released by hepatocellular carcinoma (HCC) Huh7 cells is restrained by insulin-like growth factor 1 (IGF-1) secreted from the recipient HCC HepG2 cells, which can also reduce the expression of miR-122 in Huh7 cells, thereby ensuring HepG2 cell growth." (PMID 33912560, 2021). "IGF-1, insulin-like growth factor 1; LT, liver transplantation; ECD, extended criteria donor; DMELD, donor age x Model for End Stage Liver Disease; EAD, early allograft dysfunction; DRI, Donor Risk Index; HCV, hepatitis C virus; HCC, hepatocellular carcinoma; POD, postoperative day." (PMID 26186540, 2015). "NR1I2, ESR1, ALPL, MME, IGF1, NR3C2 and PTGS2 were differentially low expressed in hepatocellular carcinoma tissues." (PMID 38842135, 2024). "We also used a GSE84402 dataset to validate the mRNA expression levels of IGF1, CDKN2A, BIRC5, and SPP1 in hepatocellular carcinoma tissues and adjacent tissues." (PMID 39042294, 2024). "It has been reported that miR-185 targets IGF1 to activate the PI3K/AKT signaling pathway in an animal model of Parkinson’s disease and induces autophagy via AKT signaling in hepatocellular carcinoma." (PMID 37834215, 2023). "We concluded that IGF1, VEGFA, and SERPINE1 had statistical significance in the expression and 10-year survival rate between hepatocellular carcinoma group and normal group." (PMID 33960267, 2021). "It has been reported that IGF1 expression was directly transactivated by NFAT1 and contributed to the progression of hepatocellular carcinoma." (PMID 34707090, 2021). "It has been reported that miR-425 promoted invasion and metastasis in hepatocellular carcinoma via modulation of SCAI, while it inhibited melanoma metastasis by negatively regulating IGF-1 through repression of PI3K-Akt pathway 25,26." (PMID 32284738, 2020). "For example, Igf1 and Mfap2, differentially expressed in I1 state, have been shown to induce EMT in hepatocellular carcinoma and in gastric cancer cells respectively." (PMID 32870263, 2020). "Several components of the IGF signaling axis, such as IGF-1, IGF-2 and IGF-1R, are deregulated during HCV-related human hepatocellular carcinoma (HCC)." (PMID 25333772, 2014). "In the present study, we demonstrated that figitumumab possesses a high affinity for IGF1R/IR heterodimeric receptors as well as IGF1 homodimer receptors and inhibits the IGF/IGF1R signaling axis in gastric cancer and hepatocellular carcinoma cells." (PMID 22438913, 2012).
hepatocellular carcinoma (continued). "In hepatocellular carcinoma, anoikis resistance of hepatoma cells has been determined to require PAK1 activity, and CAV1 could also confer resistance of hepatoma cells to anoikis by activating the IGF‐1 pathway." (PMID 36507553, 2023). "Given that miR-379 could suppress the IGF1/IGF1R and PI3K/AKT signaling pathway in hepatocellular carcinoma, and DLK1 is the potential target gene of miR-329 that may be involved in IGF1 signaling and muscle growth through Akt phosphorylation." (PMID 34527673, 2021). "GRK2 can also repress the serum-, insulin-like growth factor 1 (IGF1)-, angiotensin (Ang)II-, tumor necrosis factor (TNF) α- or PDGF-induced proliferation and migration of thyroid cancer cell lines, human hepatocellular carcinoma cells and smooth muscle cells, respectively." (PMID 34335610, 2021). "IGF-1 is produced by and promotes the cytotoxic activity of human NK cells and the expression level of IGF-1 in NK cells correlates with the cytolytic activity of NK cells from patients who have miscarried and those with hepatocellular carcinoma." (PMID 30546365, 2018). "While healthy hepatocytes do not express the IGF‐1 receptor, due to de‐differentiation, hepatoma cell lines do express the receptor and respond to IGF‐1 by phosphorylating Akt in the same way as insulin." (PMID 29263118, 2017). "Irradiation significantly upregulated the mRNA expressions of FasL, TRAIL, TNF-α, and TGF-β1 in hepatoma cells, and downregulated the mRNA expressions of IGF-1 and PDGFB, but no obvious effects on the expressions of VEGFA, PDGFA, and IL-6." (PMID 27431384, 2016). "In the present study, we investigated whether baseline serum IGF-1 levels predict time-to-progression (TTP) and overall survival (OS) in hepatocellular carcinoma (HCC) patients treated with transarterial chemoembolization (TACE)." (PMID 24595361, 2014). "Given that IRS2 is tightly involved in IGF1-induced cell migration, we then detected whether AFB1 could promote hepatoma cell migration through IGF-IR/IRS2 axis." (PMID 23112878, 2012). "Recent studies with hepatoma cells have shown that imatinib inhibits c-Abl cytosolic tyrosine kinase to attenuate insulin-induced but not IGF-1-induced phosphorylation of Akt and GSK-3β." (PMID 19693287, 2009). "Markedly elevated IGF-1 with normal GH in this clinical context strongly suggests paraneoplastic acromegaloid syndrome, as hepatic tumors – particularly hepatocellular carcinoma – can ectopically produce IGF-1 or IGF-1-like peptides independent of pituitary GH regulation." (PMID 41497147, 2026). "Notably, there was a distinctive positive correlation between the plasma GPC3 level in hepatocellular carcinoma patients and the concentration of IGF-1R which means targeting of GPC3/IGF-1 axis could be used to treat HCC." (PMID 37305177, 2023). "Increased expression levels of IGF2, IGF1 and IGFR1 were revealed in animal models of hepatocellular carcinoma (HCC)." (PMID 37298551, 2023). "Increasing evidence shows that IGF1R and its ligands (IGF‐1, IGF‐2) play an important role in the development and progression of several cancers, including hepatocellular carcinoma (HCC)." (PMID 31267557, 2019). "The effects of IGF-1 on complex V expression may be a compensatory response to mitochondrial uncoupling as IGF-1 induces uncoupling protein 2 (UCP2) expression through the PI3K/AKT/FOXO1 axis in diverse cell types including mouse adipocytes, myoblasts, and human hepatocellular carcinoma cells." (PMID 39433211, 2025). "Type 1 receptor (IGF1R) is reported to interact with insulin-like growth factor 1 and 2 (IGF1 and IGF2) for increasing fibrosis and impair liver functions from the start of preneoplastic alterations up to the developed hepatocellular carcinoma (HCC) stage." (PMID 34336665, 2021). "With its secreted ligands, IGF1 and IGF2, Insulin-like growth factor 1 receptor (IGF1R) is highly expressed in many human cancer cells, including gastric (GC) and hepatocellular carcinoma (HCC)." (PMID 22438913, 2012).
hepatocellular carcinoma (continued). "Unlike the positive correlation between IGF-1 levels and other cancers, a reduced serum level of IGF-1 has been documented in hepatocellular carcinoma (HCC)." (PMID 24586785, 2014).
Cognitive impairment (128 papers, 2009 to 2026). Abnormal cognition is characterized by deficits in thinking, reasoning, or remembering. "Serum BDNF and IGF-1 were analyzed using enzyme-linked immunosorbent assay and chemiluminescent immunoassay, and cognitive status was evaluated using the Cognitive Impairment Screening Test (CIST)." (PMID 42072914, 2026). "Lower serum IGF-1 levels at disease onset are associated with worse prognosis, increased cognitive impairment risk, and faster disease progression, suggesting that individuals who fail to exhibit an adequate IGF-1 increase experience poorer outcomes." (PMID 40595707, 2025). "In the included studies, GH and insulin-like growth factor-1 (IGF-1) are also among the hormones frequently reported to be associated with the severity of cognitive impairment." (PMID 40370784, 2025). "Increasing evidence indicates that IGF-1 plays a critical role in neurogenesis and is associated with cognitive impairment." (PMID 39963470, 2025). "Studies have shown that IGF-1 deficiency correlates with increased depressive symptoms, cognitive impairments, and amygdala hyperactivity—suggesting IGF-1 involvement in regulating anxiety responses and the stress axis." (PMID 41150816, 2025). "Previous studies have implicated IGF-1 deficiency as a key contributor to cerebrovascular dysfunction and cognitive impairment." (PMID 40360822, 2025). "Deficiency in IGF-1 during childhood and adolescence can lead to growth retardation and cognitive impairments, which can be reversed by IGF-1 injection." (PMID 39335481, 2024). "Insulin-like growth factor-1 (IGF-1) is thought to be closely associated with cognitive function, but its role in cognitive impairment caused by OSAS is unclear." (PMID 38858326, 2024). "Lower serum IGF-1 levels are associated with a higher risk of cognition impairment in a patient with CSVD." (PMID 37358957, 2023). "In humans, IGF-1 deficiency is a rare condition associated with sensorineural hearing loss, poor growth rates, and cognitive impairment." (PMID 37240591, 2023). "For instance, GH administration attenuated cognitive deficits in juvenile rats exposed to chronic and intermittent hypoxia, and this was associated with activation of IGF-1, EPO, and VEGF-A mRNAs in the hippocampus." (PMID 36232848, 2022). "The age-related loss of IGF-1 has been linked to cognitive impairment, neurodegeneration, and increased susceptibility ischemic stroke and other neurovascular pathologies." (PMID 34887742, 2021). "T2DM associated with impaired insulin and insulin-like growth factor-1 (IGF1) signaling (IIS) is a risk factor for cognitive impairment and dementia including AD." (PMID 32365816, 2020). "As both of cognitive impairment and fatigue can affect up to 70% of MS patients, we conducted this study searching for a possible association between serum IGF-1 levels on the one hand and cognition impairment as well as fatigue on the other hand." (PMID 30294204, 2018). "In the cross-sectional analysis at baseline, higher levels of IGF-1 and insulin were associated with lower cognitive scores and thus with a higher degree of cognitive impairment." (PMID 27627435, 2016). "In animal models, it was shown that decreased serum IGF-1 levels resulted in cognitive deficits and IGF-1 deficiency led to impaired learning and memory in adulthood." (PMID 26417600, 2015). "Collectively, we demonstrate that IGF‐1 deficiency promotes cerebromicrovascular dysfunction and neurovascular uncoupling mimicking the aging phenotype, which are likely to contribute to cognitive impairment." (PMID 26172407, 2015). "Physiological levels of GH and IGF‐1 support brain maturation, neurogenesis, and neural protection, but chronic GH excess can cause pathological hyperphosphorylation of the hippocampal tau protein and subsequent cognitive impairment." (PMID 41550023, 2026). "In our study, high IGF-1 levels significantly reduced the risk of cognitive impairment." (PMID 38542318, 2024).
Cognitive impairment (continued). "Furthermore, IGF-1 is directly associated with MMSE scores in older adults with cognitive impairment." (PMID 34199148, 2021). "IGF-1 expression was correlated with cognitive performance in the individuals suffering from schizophrenia, indicating that the enhanced Igf-1 expression we observed might be protective against schizophrenia-associated cognitive impairments." (PMID 33557113, 2021). "However, impaired functions of IGF1 (insulin/insulin-like growth factor) signaling, which includes insulin receptor substrates, have been recognized as a risk factor for dementia and cognitive impairment." (PMID 32050523, 2020). "Alcohol-associated cognitive impairment in the IGF-1 signaling could be a potential mechanism in the neuroinflammatory processes." (PMID 33051508, 2020). "Furthermore, prevailing evidence suggests that age-related deficiency in IGF-1 is associated with cognitive impairment, vascular rarefaction, and diminished clearance of amyloid β (Aβ)." (PMID 31732912, 2020). "Similarly, insulin-like growth factor-1 (IGF-1) is linked to the appearance of cognitive deficits, e.g., in the tasks that evaluate executive function, attention and verbal memory." (PMID 32859109, 2020). "For instance, GH or IGF-1 gene knock-out mice, compared to control animals, exhibited CNS deficits including reduced brain size, loss of myelination and specific parvalbumin-containing neurons, and cognitive impairments." (PMID 31967977, 2020). "IGF-1 deficiency with age may increase sensitivity to damage in the brain and propensity for cognitive deficits and targeting mitochondrial function in the brain may be an avenue for therapy for age-related impairment of cognitive function." (PMID 31732912, 2020). "Moreover, in human subjects affected by cognitive deficits, it was demonstrated that the reduction of IGF-1 serum levels represents a risk factor for VD and stroke." (PMID 31096580, 2019). "Also, IGF-1 has a significant positive correlation with MoCA score performance and low level of IGF-1 also was found as a risk factor for cognitive impairment in MS patients." (PMID 30294204, 2018). "Thus, it is plausible to consider that low plasma IGF-1 levels may contribute to the primary causes of cognitive disorders after TBI." (PMID 34234671, 2021). "Therefore, IGF-1 deficiency with age may increase sensitivity to damage in the brain and propensity for cognitive deficits." (PMID 31732912, 2020). "Similarly, high IGF1 plasma levels were observed in HD patients and this was associated with cognitive impairment characteristic in this disorder, however, the correlation between elevated IGF1 plasma levels and the motor and cognitive impairment in HD remains to be elucidated." (PMID 33101007, 2020). "This study demonstrates that microglial Rack1 deficiency decreased Aβ deposition and neuroinflammation and ameliorated cognitive impairments in AD model mice by enhancing IGF1‐mediated astrocytic phagocytosis." (PMID 41168999, 2026). "In this study, we demonstrated that microglial Rack1 deficiency decreased Aβ deposition and neuroinflammation and ameliorated cognitive impairments in AD model mice by enhancing IGF1‐mediated astrocytic phagocytosis." (PMID 41168999, 2026). "Altered levels of neurotrophins such as NGF, BDNF, NT3, and NT4, as well as growth factors like IGF1, VEGF, and FGF, have been associated with cognitive deficits, sensory processing abnormalities, and behavioral issues in ASD patients." (PMID 40004071, 2025). "The purpose of this study was to investigate the potential protective effect of IGF-1 on cognitive impairment in OSAS rats." (PMID 38858326, 2024). "One neuropsychological test found that in patients with type 2 diabetes combined with mild cognitive impairment, the serum IGF-1/IGFBP-3 concentration ratio was reduced, and the executive function of patients was significantly decreased." (PMID 37638322, 2023).
Cognitive impairment (continued). "In vivo studies have demonstrated IGF-1 deficiency results in increased oxidative stress, inflammation, neuronal cell death and cognitive deficits that can be improved by exogenous IGF-1." (PMID 37159450, 2023). "In mice with neuroinflammation and cognitive impairment induced by sleep deprivation, intravenous IGF-1 injection activated the PI3K/Akt/GSK-3β signaling pathway to reduce neuroinflammation and prevent cognitive decline." (PMID 37638322, 2023). "Given that these regions are critically linked to cognition, it is compelling that IGF-1 and IGF-1R deficiencies lead to cognitive impairment." (PMID 36691085, 2023). "Another study of patients with cognitive impairment showed that patients with low IGF-1 levels showed dramatically lowered Mini-Mental State Examination scores over time." (PMID 37358957, 2023). "Another study showed that subjects with mild cognitive impairment with T2D had a reduced serum IGF-1/IGFBP-3 molar ratio." (PMID 36691085, 2023). "Since IGF1 plays a crucial role in mediating dysmaturation of the DG and cognitive deficits in premature rabbits, we also postulated that the effect of oestrogen treatment is mediated by IGF1 signalling in premature kits." (PMID 37594177, 2023). "In our previous study, we also highlighted the need to examine insulin-growth factor 1 (IGF-1) as a potential biomarker for cognitive impairment and functions in CP." (PMID 35832183, 2022). "Considering this background, the aim of the present investigation is to test early IGF-1 gene therapy in both OS markers and cognitive deficits induced by TBI." (PMID 34234671, 2021). "The aim of this study was to determine the effects of a muscular strength training programme on cognitive state and IGF-1 levels in older women with mild cognitive impairment, as a function of the level of air pollution." (PMID 32859109, 2020). "Middle-aged and older males with high circulating IGF-1 levels at baseline were diagnosed with cognitive impairment after approximately 8 years in a longitudinal study." (PMID 32719587, 2020). "In men with mild cognitive impairment Baker and colleagues reported an increase in IGF-1 plasma levels and improved performance in the Trails B test in response to aerobic exercise, but not in other cognitive tests." (PMID 32785144, 2020). "IGF-1 was suggested as the possible biomarker of cognition and the decline of this molecule was related to cognitive impairment." (PMID 33392183, 2020). "The authors concluded that liver-derived circulating IGF-1 could play an important role in cognition of mice, however, they could not exclude the possibility of other endocrine/metabolic abnormalities in these gene-disrupted mice causing the cognitive deficits." (PMID 32785144, 2020). "IGF1 restoration rescues the age-related decline in hippocampal neurogenesis and cognitive impairments in rodents and represents a putative therapeutic target for neurodegenerative and neurodevelopmental disorders." (PMID 30705779, 2019). "The study aims to investigate the relation of serum IGF-1 levels with cognitive impairment and fatigue in MS patients." (PMID 30294204, 2018). "Higher serum levels of neurotrophic factors, such as brain-derived neurotrophic factor (BDNF) and insulin-like growth factor-1 (IGF-1), are associated with lower incidence of dementia and lower risk of progression in cognitive impairment in elderly people." (PMID 29751661, 2018). "Regarding cognitive function, we found that IGF-1 was significantly lower in MS patients with cognitive impairment than MS patients with normal cognitive function." (PMID 30294204, 2018). "A lower level of serum IGF-1 levels in MS patients presented with fatigue and cognitive impairment was reported." (PMID 30294204, 2018).